FBP1 (fructose-bisphosphatase 1)
Diseases named in the same sentence as FBP1 in open-access papers (continued):
Sharing a sentence is not in itself a finding about the gene and the disease.
tumor (continued). "When treated with drugs that can kill senescent cells, such as dasatinib or ABT‐263, this effect was reversed, highlighting FBP1 as a potential novel liver cancer tumour suppressor." (PMID 34137158, 2021). "FBP1 is a rate-limiting enzyme for gluconeogenesis and has recently been considered as a tumor suppressor for various cancers." (PMID 33836688, 2021). "FBP1-blunted glucose metabolism reduces NK cell viability and disarms the hold NK cells have over tumor initiation." (PMID 33995422, 2021). "Levels of FBP1 showed a 69-fold increase in tumor-infiltrated NK cells, in which glycolysis was inhibited; however, when FBP1 was inhibited, NK cell glycolysis function was restored." (PMID 34177887, 2021). "Next, we successfully established stable FBP1 overexpression in A549 cells to investigate the effect of FBP1 on LUAD tumor progression." (PMID 32439898, 2020). "Here we demonstrated that FBP1 plays a pivotal role in regulating PD-L1 expression and cancer immunity in a manner independent of its enzymatic activity, thereby defining a new role of FBP1 in regulating the process of tumor progression." (PMID 31938049, 2020). "By RNA-sequencing, western blot and glucose metabolism-related assays, we found that circFNDC3B-218aa inhibited the expression of Snail, and subsequently promoted the tumor-suppressive effect of FBP1 in CC." (PMID 32241279, 2020). "FACS analysis showed that knockdown of Fbp1 significantly decreased tumor infiltration of CD45+CD8+ T and CD45+CD4+ T cells, but increased the infiltration of CD11b+Gr1+ myeloid-derived suppressor cells (MDSCs)." (PMID 31938049, 2020). "A recent study revealed a new tumor suppressor function of FBP1 to inhibit PD-L1 expression and enhance cancer immunity." (PMID 32754266, 2020). "Tumor-infiltrating NK cells can upregulate the expression of fructose-1,6-bisphosphatase (FBP1), which impairs glycolysis, thus promoting NK cell dysfunction in the lung cancer microenvironment." (PMID 32714324, 2020). "Herein, we demonstrate that GBE1 is an important transcriptional target of HIF1α signaling and can promote tumor progression by regulating the methylation of FBP1 via the NF-κB signaling pathway in LUAD cells." (PMID 32439898, 2020). "Most importantly, we demonstrated that decreased FBP1 expression promotes tumor growth and resistance to immune checkpoint blockade therapy in mice." (PMID 31938049, 2020). "Next, we observed F4/80 (the marker of total macrophage) and CD86 (the marker of M1) by confocal laser scanning microscope, meanwhile, the level of GLUT1 and FBP1 were also detected to find out the hypoxia level and glycolysis level in the tumor." (PMID 32943999, 2020). "Consistently, PIM2 and FBP1 Ser144 phosphorylation were expressed at higher levels in the tumor samples than in the normal control samples." (PMID 32754266, 2020). "In summary, this study provides novel insight showing that hypoxia-induced HIF1α mediates GBE1 upregulation, which suppresses FBP1 expression by promoter methylation via NF-κB signaling in the tumor microenvironment of LUAD." (PMID 32439898, 2020). "FBP1 functions as a tumor suppressor via the promotion of glycogen synthesis and inhibition of glycolysis in many types of cancer." (PMID 32754266, 2020). "To investigate the effect of FBP1 on LUAD tumor progression, we first analyzed the correlation between FBP1 level and survival using the TCGA data set." (PMID 32439898, 2020). "Our previous findings showed that the gluconeogenic enzyme fructose-1,6-bisphosphatase (FBP1) is induced in NK cells during tumor development in a Kras-driven lung cancer model." (PMID 32983138, 2020). "A recent study showed that lung tumors upregulate the expression of the gluconeogenesis enzyme fructose bisphosphatase 1 (FBP1) in tumor-infiltrating NK cells through a mechanism involving TGF-β." (PMID 32038612, 2019).
tumor (continued). "In a KRas -driven tumor model in the lung, fructose-1,6-bisphosphatase (FBP1) was highly up-regulated in lung NK cells from mice bearing advanced lung tumors, compared with lung NK cells from normal mice." (PMID 31552017, 2019). "We also assessed the association between the expression of FBP1, 18F-FDG uptake tumor, and tumor differentiation grade in patients with ccRCC." (PMID 30723389, 2019). "The authors also showed that restoring FBP1 expression via HDAC inhibition was able to inhibit tumor cell growth in vitro and in vivo." (PMID 31056726, 2019). "Up-regulated FBP1 in NK cells in the tumor settings suppressed the glycolysis of NK cells, compromised their viability, and effector functions." (PMID 31552017, 2019). "In 80 studies, FBP1 was ranked by the top 10% of gene rank indicating significant statistical differences, 6 of which revealed higher expression level in tumor than normal tissues." (PMID 30867653, 2019). "In conclusion, we found that in patients with ccRCC, 18F-FDG uptake and tumor grade (from low-grade to high-grade) were both inversely correlated with FBP1 expression." (PMID 30723389, 2019). "High FBP1 expression was detected in 90.7% (49/54) of the peritumor tissues and 46.3% (25/54) of the tumor tissues." (PMID 30723389, 2019). "We thus used the medium methylation rate detected in tumor tissues as a cut-off value for FBP1 promoter region methylation level." (PMID 29984231, 2018). "The methylation ratio is also reversely correlated with the tumor differentiation, and well-differentiated tumors (high to middle grade) have statistically significant lower level of FBP1 methylation comparing to middle to low grade of tumors (p<0.01)." (PMID 29984231, 2018). "Since our data showed that FBP1 promoted c-Myc degradation, we want to investigate the role of c-Myc on FBP1-mediated tumor suppression." (PMID 30201002, 2018). "Previous studies have shown that FBP1 is downregulated in many types of solid tumors and that the restoration of FBP1 inhibits tumor cell proliferation." (PMID 30201002, 2018). "The results indicated that the up‐regulated expression of ALDOA and down‐regulated FBP1 were most significant in liver metastases compared with its primary tumour." (PMID 29992789, 2018). "Tumor cell motility, FBP1 protein and mRNA changes were investigated after BET inhibitors treatment." (PMID 30201002, 2018). "One of the key enzymes in gluconeogenesis and hypoxia, FBP1, was the dramatic reduction in ccRCC, which we found as well to oppose tumor progression." (PMID 29285300, 2017). "Fructose-1,6-biphosphatase (FBP1), a rate-limiting enzyme in gluconeogenesis, has been identified recently as a tumor suppressor in HCC and other cancer types." (PMID 28394358, 2017). "Our data showed that restoration of FBP1 decreased glucose reduction and lactate secretion and inhibited tumor cell growth." (PMID 28262837, 2017). "Groups with low and high FBP1 expression differed significantly with respect to the tumor size (P = 0.005) and AJCC stage (P = 0.001)." (PMID 28262837, 2017). "FBP1 was shown to exhibit dual tumor-suppressive functions, in gluconeogenesis as well as a HIF1A inhibitor." (PMID 29285300, 2017). "In order to deeply investigate the impact of DUOX1, GLS2, FBP1 and age on DFS and OAS, we developed a simple score composed of the four variables to predict the risk of HCC relapse and death after tumor resection." (PMID 27079415, 2016). "Then a multivariate analysis with Cox’s proportional hazard model manifested that DUOX1, GLS2, FBP1 and age were independent risk factors for the prognosis of HCC patients after tumor resection." (PMID 27079415, 2016). "In this study, we further investigate the impact of DUOX1, GLS2 and FBP1 genes expression on liver patients’prognosis after tumor resection." (PMID 27079415, 2016). "In summary, our data suggested that knockdown of FBP1 repressed the tumor progression in nude mice, probably attributable to the downregulation of c-Myc expression." (PMID 26469968, 2015).
tumor (continued). "We found that both FBP1 and c-Myc were predominantly located in the nuclei of tumor cells in the NPC samples." (PMID 26469968, 2015). "Restoring FBP1 expression partially reversed the tumor-promoting effects of NPM1, while the loss of FBP1 in PDAC tissues was indicative of a poorer prognosis." (PMID 26068981, 2015). "In summary, our study demonstrated that FBP1 is a novel biomarker and can serve as a potential predictor for tumor progression in NPC." (PMID 26469968, 2015). "A comparable effect of DNA methylation on ubiquitin carboxyl-terminal hydrolase L1 (UCHL1) and fructose-1,6-bisphosphatase-1 (FBP1) indicates that they are tumor suppressors." (PMID 25120642, 2014). "In contrast, FBP1 hypermethylation was hardly detected in normal liver cell lines and occasionally in paired adjacent non-tumor tissues, suggesting an important role of FBP1 in the pathogenesis of liver and other digestive cancers." (PMID 22039417, 2011). "Clear cell RCC was the only tumor type with a positive correlation of FBP1 and FBP3 expression levels with c-Myc expression." (PMID 19087307, 2008). "Moreover, the lipid nanoparticle (LNP)-mediated WT FBP1 mRNA delivery designed by this group can effectively inhibit tumor growth, finding a potential therapy for ccRCC and HCC." (PMID 40100307, 2025). "Moreover, FBP1 can affect tumor immune responses by regulating the number and activity of NK cells and the function of T cells." (PMID 40100307, 2025). "miR-145 targets ASTM A and FBP1 degradation to promote tumor glycolysis." (PMID 40100307, 2025). "FBP1 also inhibits multiple tumor immune escapes by down-regulating the expression of PD-L1." (PMID 40100307, 2025). "Although several PKM2 modulators have been developed, extensive preclinical and clinical studies are needed to explore the clinical application of these modulators and whether their combination with FBP1 modulators has a unique efficacy in tumor treatment." (PMID 40100307, 2025). "In addition, FBP1 can inhibit tumor immune escape by suppressing PD-L1 expression.FBP1 is also involved in mediating inflammatory responses." (PMID 40100307, 2025). "FBP1 plays a crucial role in the regulation of gluconeogenesis and constrains glycolytic flow, thus frequently exhibiting underexpression in various cancer types as a tumor suppressor." (PMID 38349431, 2024). "The overexpression of both FBP1 (WT) and FBP1 (G260R) resulted in a hindered sphere formation ability in A549 and H1299 cells, as evidenced by a reduction in the quantity and size of tumor spheres (P < 0.001)." (PMID 38349431, 2024). "Likewise, the expression of FBP1, which acts as a rate-limiting enzyme in gluconeogenesis, is commonly reduced in tumor cells." (PMID 38392212, 2024). "Additionally, the knockdown of FBP1 enhanced the capacity for tumor sphere formation, as evidenced by an increased number of spheres (P < 0.001) and larger sphere diameter (P < 0.01)." (PMID 38349431, 2024). "Notably, Cdkn1a, which codes for the cell-cycle inhibitory protein p21, and Fbp1, which codes for fructose bisphosphatase-1 identified as a tumor suppressor in ccRCC, were specifically upregulated following Vhl inactivation in CDIC, but not PT cells." (PMID 38502859, 2024). "Moreover, FBP1 appears to be a tumor suppressor in HCC progression though negatively regulating the Warburg effect." (PMID 38664521, 2024). "Furthermore, in the sphere formation assay, the number of tumor spheres formed in A549 and H1299 cells with stable overexpression of FBP1 (WT) was significantly lower compared to the control group (P < 0.001)." (PMID 38349431, 2024). "Interestingly, recent studies have revealed the intriguing mechanism through which FBP1 exerts its tumor-suppressive effects in a catalytically inactive manner." (PMID 38349431, 2024). "As a tumor suppressor, FBP1 plays a critical role in the progression of multiple tumors." (PMID 36900384, 2023).
tumor (continued). "Furthermore, in silico analysis of the EZH2 and FBP1 mRNA expressions in human CCA samples revealed that the EZH2 mRNA expression was upregulated in tumor samples, whereas the FBP1 expression was downregulated." (PMID 36900361, 2023). "Animal studies showed that expression of O-GlcNAcylation-mutant FBP1 reduced tumor growth with correspondingly enhanced cell apoptosis rates, and these effects were eliminated by mutations of PERK-phosphorylated S170 or protein phosphatase activity-required C129." (PMID 36857532, 2023). "Tumor growth in the FBP1 group was remarkably slower than that in the vector group." (PMID 36525508, 2023). "As a result, cancer cells may increase cellular glycolysis and promote lactate production to modulate the tumor microenvironment by inhibiting the expression of FBP1." (PMID 35404841, 2022). "Importantly, as a tumor suppressor, FBP1 is generally depleted in ccRCC; thus, upregulating the expression of FBP1 is a potential therapeutic strategy for cancer." (PMID 35978816, 2022). "82.5% of the EACs show FBP1 expression in the tumor albeit with different intensities categorizing specimens accordingly into score 0 (no expression), score 1 (weak expression), score 2 (moderate expression) and score 3 (strong expression) (score 1 = 25.0%, score 2 = 35.9%, score 3 = 21.5%)." (PMID 35477823, 2022). "Next, we evaluated the impact of restored expression of FBP1 on tumor growth in mice." (PMID 36237339, 2022). "In addition to FIGO stage (OR = 0.246, 95% CI: 0.080–0.627, P=0.006), tumor residual (OR = 0.564, 95% CI: 0.325–0.967, P=0.039) also showed a significant correlation with FBP1 expression." (PMID 36000567, 2022). "In addition, FBP1 expression in BLBC cells inhibited tumorigenicity in vitro and suppressed tumor formation in vivo, indicating that the loss of FBP1 is a critical oncogenic alteration in BLBC." (PMID 35954245, 2022). "So, FBP1 enzyme plays a tumor suppressive role downregulated in tumor cells." (PMID 36419156, 2022). "In general, activated NK cells are highly glycolytic, and tumor-infiltrating NK cells upregulate the expression of the gluconeogenesis enzyme fructose bisphosphatase 1 (FBP1) through a mechanism the involve TGF-β, leading to NK-cell dysfunction as glycolysis is inhibited." (PMID 36032082, 2022). "However, UCP1 reportedly can inhibit tumor progression by initiating autophagy and lipid browning programs, along with snail-mediated repression of fructose-bisphosphatase 1 (FBP1)." (PMID 35874806, 2022). "The tumors from the miR-24-1 overexpression group were smaller and weighed less than those from the empty vector-transfected and enhancer deletion groups, suggesting that miR-24-1 overexpression activated FBP1 expression to block tumor growth in a manner dependent on enhancer integrity." (PMID 35978816, 2022). "Low expression of FBP1 is directly related to a poor overall survival rate based on JavaScript:; a comprehensive profiling of TCGA dataset, indicating that FBP1 may be considered a potential prognostic biomarker in RCC as a tumor suppressor." (PMID 35978816, 2022). "In addition, FBP1 knockout reduced tumor formation in transplanted nude mice in vivo, which indicated that FBP1 promoted OC development." (PMID 36000567, 2022). "Moerover, tumour cells produce large amounts of fructose 1,6-bisphosphatase 1 (FBP1), a critical enzyme involved in gluconeogenesis in NK cells, which limits the mutually exclusive process of glycolysis process and thereby decreasing NK cytotoxicity and phenotypic dysfunction." (PMID 36578477, 2022). "Of note, a negative correlation was observed from stage I to stage III, indicating that expression of ALDOA and FBP1 may play a role in tumor progression, especially during the early stages." (PMID 35404841, 2022).
tumor (continued). "Moreover, we found that FBP1 knockdown suppressed tumor formation in nude mice and cisplatin resistance of OC cells, but the role of FBP1 in the cisplatin resistance of OC cells remained unclear." (PMID 36000567, 2022). "The product of circFNDC3B exerted its tumor-suppressive effect in Snail/FBP1/EMT axis." (PMID 35936754, 2022). "Targeting the ALDOA/FBP1 axis, it may be expected that the molecular regulation and reversal of glycolytic flux will reduce tumor malignancy." (PMID 35404841, 2022). "Targeting the ALDOA/FBP1 axis has also been considered as treatment to reduce tumor malignancy." (PMID 36077431, 2022). "Finally, we calculated the correlation coefficient of the expression levels for FBP1 and miR-24-1 in tumor tissues." (PMID 35978816, 2022). "Finally, it has been demonstrated that the deletion of the gluconeogenesis regulatory enzyme FBP1 (Fructose-1, 6-biphosphatase) induced an increment of the tumor growth, as well as an increase of the anti-PD-L1 treatment resistance." (PMID 34830179, 2021). "Taken together, these findings demonstrate that may promote tumor progression and cisplatin resistance by suppressing FBP1 expression." (PMID 34363022, 2021). "Furthermore, pretreatment of adoptively transferred NK cells with an FBP1 inhibitor dramatically enhanced their capacity to slow tumor growth and suggests a potential direction for NK cell-based immunotherapy methods." (PMID 33670082, 2021). "Thus, FBP1 weakens the cytotoxicity of tumor-infiltrated NK cells by inhibiting glycolysis; however, FBP1 can also impair the viability of tumor-infiltrated NK cells directly and independently of glycolysis." (PMID 34177887, 2021). "C-MYC-dependent downregulation of FBP1 acted as a tumor suppressor via modulating STAT3, and the C-MYC/FBP1/STAT3 axis could be a therapeutic target." (PMID 34363022, 2021). "Furthermore, co-administration of Fbp1 knockdown and anti-pd-l1 antibody additively increased the tumor infiltration of CD45+CD8+ T and CD45+CD4+ T cells and a substantial reduction of CD11b+Gr1+ MDSCs." (PMID 31938049, 2020). "As a tumor suppressor, FBP1 plays a crucial role in tumor progression in multiple cancers." (PMID 32754266, 2020). "A cancer syngeneic mouse model was utilized to examine how FBP1 affects tumor immunity." (PMID 31938049, 2020). "Moreover, FBP1 expression was markedly lower in the tumor tissues than it was in the normal lung tissues and was markedly lower in late stage (IV) LUAD tissues than it was in early stage (I, II) LUAD tissues." (PMID 32439898, 2020). "In addition, FBP1 has been reported to be a tumor suppressor that regulates tumor glucose metabolism and inhibits aerobic glycolysis, such as by increasing glucose uptake and macromolecules biosynthesis 98,103." (PMID 32549751, 2020). "In addition, previous studies have reported that this complex also accelerates degradation of two important tumor suppressors, fructose-1,6-bisphosphatase (FBP1) and 5’ adenosine monophosphate-activated protein kinase (AMPK)." (PMID 33227008, 2020). "We demonstrated that knockdown of Fbp1 promoted the tumor growth." (PMID 31938049, 2020). "Previous research also showed that although gluconeogenesis was frequently suppressed in tumors, re-expression of gluconeogenesis enzymes such as FBP1 could inhibit tumor growth." (PMID 33200655, 2020). "Moreover, detection of the protein level of GLUT1 and FBP1 indicated that the medicine reduced glucose metabolism level in tumor microenvironment." (PMID 32943999, 2020). "In the present study, we identified a novel function for FBP1 in inhibiting tumor progression and explored whether the abnormal regulation of FBP1 is involved in GBE1-induced cellular transformation and carcinogenesis." (PMID 32439898, 2020).